ATP5F1E (ATP synthase F1 subunit epsilon)
Description:
Subunit epsilon, of the mitochondrial membrane ATP synthase complex (F(1)F(0) ATP synthase or Complex V) that produces ATP from ADP in the presence of a proton gradient across the membrane which is generated by electron transport complexes of the respiratory chain. ATP synthase complex consist of a soluble F(1) head domain - the catalytic core - and a membrane F(1) domain - the membrane proton channel. These two domains are linked by a central stalk rotating inside the F(1) region and a stationary peripheral stalk. During catalysis, ATP synthesis in the catalytic domain of F(1) is coupled via a rotary mechanism of the central stalk subunits to proton translocation (Probable). In vivo, can only synthesize ATP although its ATP hydrolase activity can be activated artificially in vitro (By similarity). May be essential for the assembly of F(1) and may play an important role in the incorporation of the hydrophobic subunit c into the F(1)-c oligomer rotor of the mitochondrial ATP synthase complex.
Synonyms: ATP5E; ATPE; MC5DN3
Tractability: Small molecule: a structure with a bound ligand is known. PROTAC: ubiquitination databases record sites on it.
Gene: Protein-coding gene on chromosome 20 (59,025,475 to 59,032,358, reverse strand). Ensembl gene ENSG00000124172.
Subcellular location: Mitochondrion; Mitochondrion inner membrane
Pathways (Reactome):
Metabolism: Formation of ATP by chemiosmotic coupling
Organelle biogenesis and maintenance: Cristae formation
Gene Ontology:
Molecular function: protein binding; proton-transporting ATP synthase activity, rotational mechanism
Biological process: proton motive force-driven mitochondrial ATP synthesis; proton motive force-driven ATP synthesis
Cellular component: mitochondrion; proton-transporting ATP synthase complex; mitochondrial inner membrane; mitochondrial matrix
Genetic constraint (gnomAD): Loss-of-function variants: 5 observed, 6.02 expected, observed/expected ratio (o/e) 0.83, 90% interval 0.43 to 1.65. That is too few expected variants to judge how well the gene tolerates losing a copy. Missense variants: 59 observed, 56.92 expected, observed/expected ratio (o/e) 1.04, 90% interval 0.84 to 1.29. Synonymous variants: 20 observed, 21 expected, observed/expected ratio (o/e) 0.95, 90% interval 0.67 to 1.38.
Gene-disease validity (ClinGen):
ClinGen rates the evidence that ATP5F1E causes each of these diseases.
mitochondrial disease (autosomal recessive): Limited.
Homologues: Orthologues: chimpanzee ATP5F1E (98% identical), dog ATP5F1E (96% identical), guinea pig ATP5F1E (96% identical), macaque ATP5F1E (96% identical), rabbit ATP5F1E (94% identical), mouse Atp5f1e (90% identical), rat Atp5f1e (88% identical), rat LOC100361879 (88% identical).
Diseases named in the same sentence as ATP5F1E in open-access papers:
ATP5F1E is named in the same sentence as 39 diseases in open-access papers, as found by Europe PMC text mining. Sharing a sentence is not in itself a finding about the gene and the disease. The quoted sentences say what the papers report.
COVID-19 (4 papers, 2021 to 2024). A disease caused by infection with severe acute respiratory syndrome coronavirus 2. "A significant increase in expression of ATP5F1E in COVID-19 patients has been reported, which might be related to elevated production of ROS and increased inflammation." (PMID 38295140, 2024). "Interestingly, we also found that ATP synthesis-related genes (e.g., ATP5F1A, ATP5F1B, ATP5F1C, ATP5F1D, ATP5F1E) were significantly increased in COVID-19 patients." (PMID 37087411, 2023).
tumor (7 papers, 2015 to 2025). "ATP5F1E facilitates ATP production and supports tumor proliferation under energy-deficient conditions." (PMID 40989695, 2025).
ATP5F1E also shares sentences with these, for which no sentence is quoted: tuberculosis (5 papers); cancer (4); infection (4); colon cancer (2); leukemia (2); Parkinson disease (2); prostate carcinoma (2); Alzheimer disease (1); asthma (1); autism (1); breast carcinoma (1); cardiac hypertrophy (1); cardiomyopathy (1); cerebral edema (1); Cerebral ischemia (1); CLN3 disease (1); colorectal cancer (1); endometrioid carcinomas (1); energy metabolism disorders (1); heart failure (1); ischemia (1); Macrothrombocytopenia (1); melanoma (1); metastatic tumors (1); mitochondrial disease (1); myeloma (1); myocarditis (1); NARP syndrome (1); Neurological Disorders (1); nonalcoholic fatty liver disease (1).
A further 7 diseases each share a sentence with ATP5F1E in 1 paper.